LINC00364 (long independently transcribed non-coding RNA 364)
Synonyms: LncRNA00364
Gene: Long non-coding RNA gene on chromosome 13 (67,326,177 to 67,379,994, forward strand). Ensembl gene ENSG00000230040.
Diseases named in the same sentence as LINC00364 in open-access papers:
LINC00364 is named in the same sentence as 1 disease in open-access papers, as found by Europe PMC text mining. Sharing a sentence is not in itself a finding about the gene and the disease.
LINC00364 shares sentences with these, for which no sentence is quoted: tumor (1 paper).